SCN1A (sodium voltage-gated channel alpha subunit 1)
Diseases named in the same sentence as SCN1A in open-access papers (continued):
Sharing a sentence is not in itself a finding about the gene and the disease.
Dravet syndrome (496 papers, 2009 to 2026). "The most clearly understood DEE, Dravet syndrome, has the same clinically recognizable core phenotype in almost every affected patient, most of whom carry loss‐of‐function variants in SCN1A." (PMID 40836506, 2026). "Severe myoclonic epilepsy of infancy (SMEI, Dravet syndrome), which is mainly caused by the SCN1A mutation, is a severe epileptic encephalopathy that manifests in infancy and leads to intractable seizures and developmental impairment." (PMID 41574838, 2026). "Dravet syndrome is an epileptic encephalopathy most often caused by loss-of-function mutations in the SCN1A gene, leading to haploinsufficiency of the voltage-gated sodium channel NaV1.1." (PMID 41727118, 2026). "Dravet syndrome (DS) is a rare and severe childhood-onset developmental epileptic encephalopathy caused primarily by mutations in the sodium channel gene SCN1A." (PMID 42051158, 2026). "Variants in genes linked to Brugada syndrome (SCN5A), LQT3 (SCN5A), and Dravet syndrome (SCN1A) are also reported in SUDEP cohorts." (PMID 40234944, 2025). "SCN1A mutations, often associated with Dravet syndrome, disrupt sodium channel function and lead to prolonged seizures and autonomic instability, which increase the risk of bradycardia and other arrhythmias." (PMID 40867142, 2025). "For example, loss‐of‐function variants in SCN1A are strongly associated with Dravet syndrome, a condition characterized by marked drug resistance." (PMID 40746153, 2025). "Dravet syndrome (DS) is associated with a loss-of-function (LoF) missense mutation at the Scn1a gene and is a severe form of epilepsy with a high incidence of SUDEP." (PMID 40004062, 2025). "Dravet syndrome presents in early childhood with a mix of focal and generalized seizures, often related to mutations in the SCN1A gene." (PMID 40217881, 2025). "Examples of somatic editing include editing SCN1A mutations in Dravet syndrome or targeting EGFRvIII mutations in glioblastomas—both of which are highly promising therapeutic candidates." (PMID 40806492, 2025). "For example, SCN1A-associated Dravet syndrome variants exhibited 3D positional correlations with SCN2A variants associated with autism (R = 0.31, P = 4.7e − 35), and Brugada syndrome variants in SCN5A (R = 0.29, P = 6.1e − 40)." (PMID 40624578, 2025). "This phenomenon is well characterized in patients with SCN1A mutations, which show a range of phenotypes from FS to Dravet syndrome." (PMID 40529445, 2025). "These SCN1A mutations are associated with genetic epilepsies, including Dravet syndrome (DS)/severe myoclonic epilepsy in infancy (SMEI) and genetic epilepsy with febrile seizures plus (GEFS+)." (PMID 41007641, 2025). "Dravet Syndrome (DS) is a severe genetic epileptic encephalopathy caused by mutations in the SCN1A gene that encodes the voltage-gated sodium channel (NaV1.1) subunit alpha." (PMID 41511350, 2025). "Supporting this mechanism, similar effects have been observed in NaV1.1‐deficient mice (Scn1a+/− mice; NaV1.1 encoded by Scn1a, Dravet syndrome models), where 5% CO2 reduced seizure duration and increased expression of the ASIC1a protein in the hippocampus." (PMID 41342230, 2025). "In Dravet Syndrome caused by SCN1A-loss-of-function variants, sodium channel blockers should be avoided." (PMID 40429983, 2025). "SCN1A loss-of-function variants cause Dravet syndrome (the most common monogenic DEE), whereas rarer gain-of -function variants lead to an early infantile DEE with hyperkinetic movement disorder and other features." (PMID 40381056, 2025). "Mutations in genes like SCN1A are commonly associated with Dravet syndrome, which disrupt neuronal and cardiac excitability and increase the likelihood of prolonged seizures and autonomic instability." (PMID 40867142, 2025).
Dravet syndrome (continued). "At the same time, we examined the form of SCN1A mutations based on previous studies in Dravet syndrome and found that they were in the form of missense mutations, with no major genetic mutations such as truncation mutations or deletion mutations." (PMID 40003892, 2025). "Dravet syndrome is a developmental and epileptic encephalopathy associated with pathogenic variants in SCN1A." (PMID 39946203, 2025). "These SCN1A-related Dravet syndrome disorders lie at different ends of the SCN1A–disease spectrum, reflecting the degree of a loss of function in inhibitory interneurons." (PMID 40003892, 2025). "Dravet syndrome (DS) is a severe developmental and epileptic encephalopathy, with most cases caused by heterozygous loss-of-function mutations in the SCN1A gene, resulting in haploinsufficiency." (PMID 41007641, 2025). "Dravet Syndrome (DS) is a catastrophic childhood developmental epileptic encephalopathy that is caused mostly (~70–80%) by de novo mutations in the SCN1A gene." (PMID 41511350, 2025). "On the other hand, Dravet syndrome is caused by in most cases known mutations in the voltage‐gated sodium channel gene SCN1A." (PMID 37594756, 2024). "Focal cortical dysplasia (n = 2) was the most common in patients with structural brain lesions and Dravet syndrome with SCN1A mutations (n = 2) was the most common epilepsy syndrome in the genetic group." (PMID 38689875, 2024). "80% of Dravet syndrome patients harbor mutations in SCN1A that encodes sodium channel subunit NaV1.1." (PMID 38959711, 2024). "Most patients with Dravet syndrome have mutations involving the voltage-gated sodium channel alpha (I) gene SCN1A." (PMID 38983583, 2024). "A drug‐naive SCN1A Dravet syndrome mouse model demonstrated impaired sleep homeostasis secondary to the loss of Nav1.1 channels in the inhibitory forebrain GABAergic neurons, implicating the gene's involvement in sleep disruption." (PMID 39361253, 2024). "Next, we investigated the mechanisms of action of a known pathogenic variant in SCN1A, haploinsufficiency of which causes a developmental epileptic encephalopathy called Dravet syndrome (MIM: 607208)." (PMID 39084224, 2024). "Thirty patients with Dravet syndrome (aged 3–21 years, 12 females) with a verified pathogenic SCN1A variant were included." (PMID 39140199, 2024). "SCN1A mutation-positive Dravet syndrome patients were prospectively followed up in the UK from 2010 to 2020." (PMID 38229878, 2024). "Human genetic studies showed that a fraction of SCN1A mRNA contains exon 20 N that triggers nonsense-mediated decay, and if the inclusion is abnormally increased by human mutations, it causes Dravet syndrome." (PMID 39119251, 2024). "Dravet syndrome, which is due to SCN1A variants in >80% of individuals, is the epitome of this and not surprisingly where intronic discoveries have been made." (PMID 38129960, 2024). "For pathogenic variants in the neuronal sodium channel α1 subunit gene (SCN1A), the time of onset has been found to contribute to discriminating between Dravet syndrome and GEFS++." (PMID 38474157, 2024). "For example, Dravet syndrome in humans is caused by heterozygous loss-of-function mutations in the SCN1A (sodium voltage-gated channel alpha subunit 1) gene." (PMID 39079985, 2024). "A recent meta‐analysis of seven published trials on the use of an add‐on ketogenic diet in people with Dravet syndrome (of which 80–100% had an SCN1A mutation) revealed good efficacy of this treatment." (PMID 37594756, 2024). "Dravet syndrome is a severe infantile onset developmental and epileptic encephalopathy associated with mutations in the sodium channel alpha 1 subunit gene SCN1A." (PMID 38229878, 2024). "Among genetic neurodevelopmental encephalopathies, diffuse background slowing appears to increase with age in Dravet syndrome, an infantile-onset developmental and epileptic encephalopathy due to pathogenic variants in the SCN1A gene." (PMID 38505260, 2024).
Dravet syndrome (continued). "The gene with the highest reported number of DNMs was SCN1A which encodes the sodium voltage-gated channel alpha subunit 1 involved in severe myoclonic epilepsy of infancy or Dravet syndrome." (PMID 38395944, 2024). "Over 80% of individuals with Dravet syndrome have de novo pathogenic variants in the SCN1A gene that encodes the NaV1.1 voltage-gated sodium channel." (PMID 38862622, 2024). "ETX101 is a recombinant adeno-associated viral (AAV) vector containing a GABA regulatory element designed to upregulate SCN1A (encoding the voltage-gated sodium channel NaV1.1) and restore interneuron function in patients with Dravet Syndrome." (PMID 38449810, 2024). "Inhibitory interneuron dysfunction has been heavily implicated in Dravet syndrome, another sodium channelopathy resulting from mutations in the SCN1A gene." (PMID 39435659, 2024). "Dravet syndrome is a severe epilepsy disorder characterized by drug-resistant seizures and cognitive dysfunction, often caused by SCN1A gene mutations." (PMID 38167335, 2024). "The aim of this study was to characterize the genotype and phenotype heterogeneity of patients with SCN1A gene mutations in the Polish population, fulfilling the criteria for the diagnosis of Dravet syndrome (DRVT)." (PMID 38785537, 2024). "This article focuses on manifestations in two Indonesian children with Javanese ethnicity who experienced Dravet syndrome with an SCN1A gene mutation, presenting genetic analysis findings using next-generation sequencing." (PMID 38649973, 2024). "Dravet syndrome (DS) is a devastating early-onset refractory epilepsy syndrome caused by variants in the SCN1A gene." (PMID 39190448, 2024). "Loss-of-function mutations in SCN1A have been observed in most cases of Dravet syndrome (DS), manifesting as epileptic seizures, hyperactivity, autistic traits, and cognitive decline." (PMID 39280100, 2024). "For instance, mutations in the SCN1A locus can lead to Dravet syndrome, generalized epilepsy with febrile seizures plus (GEFS+), and other epilepsy phenotypes." (PMID 37927689, 2023). "For instance, truncating mutations in SCN1A lead to earlier seizures in Dravet syndrome when compared to missense mutations." (PMID 38003469, 2023). "Dravet syndrome is a severe developmental and epileptic encephalopathy mostly caused by heterozygous mutation of the SCN1A gene encoding the voltage-gated sodium channel α subunit Nav1.1." (PMID 35414300, 2023). "Loss-of-function mutations in SCN1A, the gene that encodes Nav1.1, are present in the majority of Dravet syndrome patients." (PMID 36701411, 2023). "The more common SCN1A loss-of-function mutations are associated with epileptic encephalopathies (e.g., Dravet syndrome) with a range of severity partly reflecting the severity of mutation." (PMID 37551713, 2023). "Dravet syndrome is a genetic developmental epileptic encephalopathy caused mainly by mutations in the SCN1A gene." (PMID 37483446, 2023). "Dravet syndrome (Dravet) is a severe congenital developmental genetic epilepsy caused by de novo mutations in the SCN1A gene." (PMID 37206664, 2023). "For example, SCN1A mutations are linked to Dravet syndrome, while mutations in KCNQ2 and KCNQ3 are associated with benign familial neonatal epilepsy." (PMID 37927689, 2023). "We also compared PRS for intelligence, longevity, and epilepsy between GEL SCN1A controls and the 13 Dravet syndrome cases with SCN1A missense variants." (PMID 37006128, 2023). "For example, mutations in the SCN1A gene are associated with Dravet syndrome, while mutations in the KCNQ2 and KCNQ3 genes are linked to benign familial neonatal epilepsy (BFNE)." (PMID 37927689, 2023).
Dravet syndrome (continued). "The present study identified a prominent SD phenotype and disturbed motor behavior associated with these depolarizing events in the Scn1a-deficient mouse model of Dravet syndrome." (PMID 37551713, 2023). "While SCN1A-LOF is associated with Dravet syndrome, SCN1A-GOF causes familial hemiplegic migraine type 3 (FHM3) or a spectrum of DEE including movement disorder and arthrogryposis (NDEEMA)." (PMID 36877742, 2023). "Dravet syndrome is typically considered monogenic, but shows marked phenotypic heterogeneity that is incompletely explained by differences in the causal SCN1A variant." (PMID 37006128, 2023). "Nine patients (eight patients with Dravet syndrome with SCN1A mutations and one patient with Rasmussen encephalitis) were included because of convulsive status epilepticus needing hospitalization." (PMID 37712338, 2023). "Mutations in the SCN1A gene are linked to Dravet syndrome, manifesting as partial or generalized epilepsy with febrile seizures." (PMID 38003469, 2023). "FHM3 is caused by mutations in the SCN1A gene (sodium voltage-gated channel alpha subunit 1) coding for a sodium channel and has been related to epilepsy syndromes such as Dravet syndrome and generalized epilepsy with febrile seizures plus." (PMID 37685382, 2023). "Five GEL SCN1A controls carried SCN1A missense variants that have previously been reported in association with epilepsy syndromes, including Dravet syndrome, or sudden unexpected death." (PMID 37006128, 2023). "Dravet syndrome is an archetypal rare severe epilepsy, considered ‘monogenic’, typically caused by loss-of-function SCN1A variants." (PMID 37006128, 2023). "Over 80% of cases of Dravet Syndrome (DS) are caused by SCN1A variants, and 80–90% of these arise through de novo mutations." (PMID 37139072, 2023). "For instance, in patients with SCN1A mutations and Dravet syndrome, sodium channel-blocking AEDs like stiripentol have shown better efficacy." (PMID 37927689, 2023). "Dravet syndrome (DS) is an epileptic encephalopathy caused by mutations in the Scn1a gene encoding the α1 subunit of the Nav1.1 sodium channel, which is associated with recurrent and generalized seizures, even leading to death." (PMID 36769051, 2023). "Consistent with the effects of the SCN1A gene mutation observed in mouse models of Dravet syndrome, this finding confirms impaired gamma oscillatory activity as a relevant marker of the disease." (PMID 36639812, 2023). "LEV can effectively alleviate seizures in eyelid myoclonia of Jeavons syndrome, Dravet syndrome with mutation of SCN1A, and PCDH19 Girls Clustering Epilepsy." (PMID 37880614, 2023). "Remarkably, this study identified SCN1A variants in all subjects, establishing Dravet Syndrome as the prototypical SCN1A channelopathy." (PMID 37139072, 2023). "Dravet syndrome (DS) is an SCN1A mutation-related, infantile-onset epilepsy syndrome, characterized by a distinctive seizure history: prolonged febrile or afebrile seizures beginning in the first year of life, followed by subsequent multiple seizure types." (PMID 37745659, 2023). "SCN1A mutation was previously reported in a Saudi girl diagnosed with Dravet syndrome who had seizures at eight months of age in response to fever, illness, and diaper changing." (PMID 37628333, 2023). "Mutations in the SCN1A gene, which encodes the sodium channel Nav1.1, are the primary genetic cause of Dravet syndrome." (PMID 37927689, 2023). "Epileptiform activity in Dravet syndrome, caused by impaired expression of the SCN1A gene (alpha subunit of sodium channel protein type 1), can be stopped with high efficiency by stiripentol." (PMID 38069426, 2023). "It is also possible for a GEFS+ phenotype to be caused by a de novo SCN1A mutation in one generation, only for the proband’s progeny to inherit the same variant and have a much more severe phenotype, up to and including Dravet syndrome." (PMID 37834053, 2023).
Dravet syndrome (continued). "To demonstrate the potential of our model, we studied neuronal networks derived from a Dravet syndrome (DS) patient with a missense mutation in SCN1A, encoding sodium channel NaV1.1." (PMID 37419110, 2023). "In mice, loss-of-function Scn1a mutations caused clinical features reminiscent of Dravet syndrome, including early-onset epileptic seizures, hyperactivity, learning and memory deficits, reduced sociability and ataxic gaits and premature sudden death." (PMID 37219072, 2023). "As previously discussed, Dravet Syndrome (DS) is an NDD caused by haploinsufficiency of the SCN1A voltage-gated Na2+ channel." (PMID 36792602, 2023). "Prior work has established that Dravet syndrome (DS) is largely due to heterozygous pathogenic loss-of-function variants in SCN1A leading to haploinsufficiency of the voltage-gated sodium channel α subunit Nav1.1." (PMID 35212623, 2022). "For example, in the context of Dravet syndrome (caused by loss of function mutations in SCN1A), we showed that Scn1a transcript is expressed by inhibitory parafacial neurons in the region of the RTN." (PMID 36605420, 2022). "These include rodents with mutations in the SCN1A gene (mimics Dravet syndrome), SCN5A gene (mimics Brugada syndrome), KCNH2, KCNQ1 genes (mimics Long QT syndrome), etc.." (PMID 35754505, 2022). "Recently, a study of Dravet Syndrome, which is most commonly caused by haploinsufficiency in SCN1A, found that rescue of SCN1A gene expression in both immature and mature interneurons was capable of rescuing excitability defects." (PMID 36183905, 2022). "We also identified dramatic gene expression alterations, including those associated with astrogliosis in Dravet syndrome mice, that, accordingly, were rescued by Scn1a gene expression normalization at P30." (PMID 35013317, 2022). "For example, Dravet syndrome, the archetypal monogenic epileptic encephalopathy, is typically caused by mutations in SCN1A." (PMID 36196775, 2022). "Pathogenic variants in SCN1A result in a spectrum of phenotypes ranging from mild febrile seizures to Dravet syndrome, a severe infant-onset epileptic encephalopathy." (PMID 35606653, 2022). "Dravet syndrome is a severe epileptic encephalopathy caused primarily by haploinsufficiency of the SCN1A gene." (PMID 35013317, 2022). "Screening for ATP6V0C mutations would help differentiating patients with Dravet syndrome caused by SCN1A mutations, which presented similar clinical manifestation but different responses to antiepileptic treatment." (PMID 35600075, 2022). "It was approved for use in the treatment of seizures associated with SCN1A Dravet syndrome (and subsequently for Lennox-Gastaut Syndrome) in patients 2 years of age and older with a warning of valvular heart disease and pulmonary hypertension." (PMID 36291443, 2022). "Haploinsufficiency for SCN1A is a major cause of Dravet syndrome, and yet there is variable expressivity among patients with this shared genetic basis." (PMID 35606653, 2022). "SCN1A has been associated with several epilepsy syndromes with distinct clinical severities, especially the Dravet syndrome (DS), a refractory childhood epilepsy characterized by intractable seizures, developmental disorders, and increased mortality." (PMID 35819063, 2022). "Photosensitivity is considered a characteristic of Dravet syndrome, and many cases of SCN1A mutations have been described with photosensitivity." (PMID 36034301, 2022). "Heterozygous deletion of Scn1a (Scn1a+/-) in mice replicates the phenotypes of Dravet syndrome patients, including susceptibility to hyperthermia-induced seizures." (PMID 34980287, 2022). "Inhibition of Cav3.1 has been suggested as a novel target for Dravet syndrome as knockout of Cacna1g, which encodes Cav3.1, diminished spontaneous seizures and improved survival of Scn1a+/– mice." (PMID 36386164, 2022).